PRSS12 (serine protease 12)
Description:
Plays a role in neuronal plasticity and the proteolytic action may subserve structural reorganizations associated with learning and memory operations.
Synonyms: BSSP-3; MRT1; BSSP3
Tractability: Small molecule: a high-quality ligand is known; it belongs to a druggable protein family. Antibody: UniProt places it where antibodies can reach, with medium confidence; UniProt predicts a signal peptide or a membrane-spanning region; its Gene Ontology location is reachable by antibodies, with medium confidence. PROTAC: a small molecule that binds it is known.
Target class: Enzyme; Hydrolase
Gene: Protein-coding gene on chromosome 4 (118,280,038 to 118,353,003, reverse strand). Ensembl gene ENSG00000164099.
Subcellular location: Secreted
Gene Ontology:
Molecular function: serine-type endopeptidase activity; serine-type peptidase activity; peptidase activity
Biological process: exocytosis; zymogen activation; proteolysis
Cellular component: glutamatergic synapse; presynapse; axon; dendrite; plasma membrane; synaptic cleft; terminal bouton; cytoplasmic vesicle; extracellular region; membrane; Schaffer collateral - CA1 synapse; synapse
Genetic constraint (gnomAD): Loss-of-function variants: 83 observed, 103.22 expected, observed/expected ratio (o/e) 0.8, 90% interval 0.67 to 0.96. The upper end of that interval is the gene's LOEUF score, 0.96, which puts it in group 4 of 6, group 1 being the genes least tolerant of losing a copy. Missense variants: 1,103 observed, 1,115.1 expected, observed/expected ratio (o/e) 0.99, 90% interval 0.94 to 1.04. Synonymous variants: 438 observed, 404.61 expected, observed/expected ratio (o/e) 1.08, 90% interval 1 to 1.17.
Gene-disease validity (ClinGen):
ClinGen rates the evidence that PRSS12 causes each of these diseases.
non-syndromic intellectual disability (autosomal recessive): Limited. An intellectual disability that is not part of a larger syndrome.
Homologues: Orthologues: chimpanzee PRSS12 (99% identical), macaque PRSS12 (98% identical), pig PRSS12 (91% identical), rabbit PRSS12 (88% identical), dog PRSS12 (85% identical), rat Prss12 (72% identical), mouse Prss12 (72% identical), guinea pig PRSS12 (70% identical), tropical clawed frog prss12 (67% identical), zebrafish prss12 (57% identical). Paralogues in human: DMBT1 (29% identical), SSC5D (26% identical), CD163 (26% identical), CD163L1 (25% identical), SCART1 (22% identical), LOXL2 (19% identical), LOXL3 (19% identical), LOXL4 (19% identical), SSC4D (18% identical), CD6 (14% identical), CD5L (13% identical), CD5 (11% identical), and 3 more.
Diseases named in the same sentence as PRSS12 in open-access papers:
PRSS12 is named in the same sentence as 19 diseases in open-access papers, as found by Europe PMC text mining. Sharing a sentence is not in itself a finding about the gene and the disease. The quoted sentences say what the papers report.
mental retardation (3 papers, 2016 to 2023). "Mutations in the remaining four genes, namely, SLCO1B1, CNGA1, PRSS12, and PEX1, have associations with autosomal diseases, such as autosomal recessive retinitis pigmentosa and non-syndromic intellectual disability." (PMID 35912179, 2022). "In addition, expression of a truncated version of PRSS12, another down-regulated DEG, results in symptoms of mental retardation in humans, while PRSS12 knock outs lead to impaired long-term memory formation in Drosophila and mice." (PMID 27809765, 2016).
cognitive deficits (2 papers, 2016 to 2022). "PRSS12 encodes for the neurotrypsin protein secreted from neuronal cells and has been implicated in synaptic plasticity, learning, memory and cognitive impairment." (PMID 36777645, 2022).
influenza (2 papers, 2012 to 2017). An acute viral infection of the respiratory tract, occurring in isolated cases, in epidemics, or in pandemics; it is caused by serologically different strains of viruses (influenzaviruses) designated A, B, and C, has a 3-day incubation period, and usually lasts for 3 to 10 days. "In this study, MST1 and PRSS12 were implicated in CRE/CREB signaling; however, in response to influenza infection, CRE signaling levels in cells treated with siPRSS12 were unchanged compared to both pathway reporter and siNEG controls." (PMID 22606348, 2012).
autism (1 paper, 2022). Persistent deficits in social interaction and communication and interaction as well as a markedly restricted repertoire of activity and interest as well as repetitive patterns of behavior.
epilepsy (1 paper, 2020). A brain disorder characterized by episodes of abnormally increased neuronal discharge resulting in transient episodes of sensory or motor neurological dysfunction, or psychic dysfunction. "Thus, L2–3_Cux2 and L5–6_Fezf2 subtypes co-clustered with Sst_Tac1 and Vip_Cbln1 subtypes, whereas L3_Cux2_Prss12 co-clustered with Pvalb_Sulf1, which might underlie local neuronal networks with most strongly affected in the epilepsy transcriptome." (PMID 33028830, 2020).
glioma (1 paper, 2012). A benign or malignant brain and spinal cord tumor that arises from glial cells (astrocytes, oligodendrocytes, ependymal cells). "PRSS12 encodes a protease that can activate tissue plasminogen activator (tPA), an enzyme that is highly expressed by glioma cells and has been suggested to promote invasion." (PMID 23046790, 2012).
hepatocellular carcinoma (1 paper, 2023). A malignant tumor that arises from hepatocytes. "For example, PRSS12 in Panc-AdenoCA, ABCC11 in liver hepatocellular carcinoma (Liver-HCC), and NOD2 in skin melanomas (Skin-Melanoma) show tissue-specific expression patterns." (PMID 38143269, 2023).
neuroblastoma (1 paper, 2020). Neuroblastoma (NB) is the most common solid, extracranial childhood tumor. "Our result support that upregulation of PRSS12 is indicative of poor survival in neuroblastoma." (PMID 33245713, 2020).
sarcopenia (1 paper, 2023). Progressive decline in muscle mass due to aging which results in decreased functional capacity of muscles. "Changes in PRSS12 expression have also been associated with extracellular matrix remodelling, a potential contributor to the development of sarcopenia." (PMID 36609795, 2023). "Accordingly, we explored whether genes encoding agrin (AGRN) and neurotrypsin (PRSS12) were associated with sarcopenia phenotypes: muscle mass, strength and plasma C-terminal agrin fragment (CAF)." (PMID 36609795, 2023). "In light of this, we aimed to determine whether AGRN and/or PRSS12 were associated with sarcopenia phenotypes including muscle mass, strength and plasma CAF levels." (PMID 36609795, 2023). "Therefore, the single-variant and gene-burden results complement the WGS data, illustrating that both common intronic and rare exonic AGRN/PRSS12 variants associate with phenotypes relevant to sarcopenia." (PMID 36609795, 2023). "With this in mind, it seems logical that PRSS12 would be associated with circulating CAF levels and other sarcopenia-related phenotypes through its role in NMJ degradation." (PMID 36609795, 2023). "We hope our findings encourage future endeavours to further explore the potential role of AGRN and PRSS12 in sarcopenia pathogenesis." (PMID 36609795, 2023). "Our findings provide novel evidence of the relevance of AGRN and PRSS12 to sarcopenia phenotypes and support existing physiological data illustrating the importance of the NMJ in maintaining muscle health during ageing." (PMID 36609795, 2023). "Nevertheless, it is noteworthy that the effects of AGRN and PRSS12 on sarcopenia phenotypes are likely to be synergistic, whereby changes in PRSS12 expression may stimulate changes in AGRN expression." (PMID 36609795, 2023). "For example, studies have observed the onset of sarcopenia in old mice to be accompanied by a significant increase in PRSS12 expression while another study reported over-expression of PRSS12 to induce NMJ fragmentation and precocious sarcopenia." (PMID 36609795, 2023).
tumor (3 papers, 2020 to 2025). "In addition, ALOX15B, LCN2, PRSS12, CD79B and ITSN2 showed tumor lesion-specific changes for all four patients." (PMID 37488117, 2023).
PRSS12 also shares sentences with these, for which no sentence is quoted: autosomal recessive retinitis pigmentosa (1 paper); behavioral disorders (1); colon cancer (1); melanoma (1); neurodevelopmental disorder (1); pneumonia (1); schizophrenia (1); skin melanomas (1); upper respiratory infections (1).